NFIA (nuclear factor I A)
Diseases named in the same sentence as NFIA in open-access papers (continued):
Sharing a sentence is not in itself a finding about the gene and the disease.
Ventriculomegaly (5 papers, 2007 to 2022). An increase in size of the ventricular system of the brain. "For example, de novo P/LP variants in the NFIA gene were identified in two fetuses (cases 4 and 19) with agenesis of the corpus callosum and ventriculomegaly by prenatal ultrasound and brain MRI at the gestational age of 33 and 22 weeks, respectively." (PMID 36307859, 2022). "NFIA haploinsufficiency has been associated with ventriculomegaly, corpus callosum hypogenesis, abnormal external genitalia, and intrauterine growth restriction in a fetus." (PMID 36307859, 2022). "Indeed, all five individuals with NFIA haploinsufficiency exhibited hydrocephalus or ventriculomegaly." (PMID 17530927, 2007). "NFIA gene (OMIM*600727) has been shown to be associated with a syndrome of central nervous system malformations (corpus callosum and ventriculomegaly) with or without urinary tract defects(BRMUTD) (OMIM#613735) with a low incidence." (PMID 32926563, 2020). "Our results establish that NFIA haploinsufficiency is a likely contributor to a range of CNS defects, including ACC, hydrocephalus, ventriculomegaly, Chiari type I malformation, and tethered spinal cord, and that renal defects can also result from a disturbance in ureteral development." (PMID 17530927, 2007). "While comparing the clinical features of our patient with the two half-siblings who have a larger microdeletion including NFIA, we found that DGDP005 does not manifest ventriculomegaly, tethered spinal cord, Chiari I malformation, or urinary tract defects." (PMID 26997977, 2016).
astrocytoma (4 papers, 2016 to 2024). "In astrocytoma, the high expression of NFIA contributes to improved progression-free survival and overall survival for patients." (PMID 36713370, 2022). "The NFIA gene encodes a member of the nuclear factor 1 (NF1) family of transcription factors, and has been associated with cancer prognosis in some cancers, such as astrocytomas, and may be associated positively or negatively with prognosis depending on the tumor type." (PMID 33092094, 2020). "In pathology, NFIA and NFIB are known to induce cellular differentiation in high-grade astrocytoma." (PMID 39404397, 2024).
atherosclerosis (4 papers, 2019 to 2025). A disease characterized by the build-up of fatty material and calcium deposition in the arterial wall resulting in partial or complete occlusion of the arterial lumen. "The lncRNA, RP5‐833A20.1, was found to be involved in the regulation of atherosclerosis development and was associated with elevated miR‐382‐5p levels, and the inhibition of nuclear factor IA (NFIA) expression." (PMID 33052009, 2020). "Overexpression of NFIA decreased the circulation of inflammatory cytokines, including IL‐6 and TNF‐α, and promoted regression of atherosclerosis in apolipoprotein E‐deficient mice, possibly through the nuclear factor kappa B (NF‐κB) pathway." (PMID 40560736, 2025). "It is generally accepted that NFIA regulates cholesterol homeostasis and reverses atherosclerosis progression in CVD." (PMID 33052009, 2020). "For instance, nuclear factor IA (NFIA) regulates cholesterol homeostasis in the body and promotes the progression of atherosclerosis through the lncRNA RP5833A20.1 sponging miR-382-5p, which targets NFIA axis." (PMID 31739782, 2019). "For example, the nuclear factor IA (NFIA) regulates cholesterol homeostasis in the body, promoted progression of atherosclerosis through the lncRNA RP5833A20.1 sponging miR-382-5p targeting NFIA axis." (PMID 31182968, 2019).
breast carcinoma (4 papers, 2014 to 2020). "In the present study, high expression of NFIA, NFIB and NFIX was significantly associated with improved prognosis in breast cancer." (PMID 32219034, 2020). "Decreased NFIA mRNA expression indicated better OS, RFS and DMFS in breast cancer patients with HER2+ subtype but worse OS, RFS and DMFS in luminal A subtype patients." (PMID 32219034, 2020).
colorectal cancer (4 papers, 2017 to 2022). A primary or metastatic malignant neoplasm that affects the colon or rectum. "Up-regulation of NFIA can slow the development of colorectal cancer through inhibiting cancer cell proliferation and metastasis." (PMID 36035369, 2022). "LINC00511 was also reported to play an oncogenic role via upregulating and downregulating nuclear factor I/A (NFIA) and interleukin 24 (IL-24), respectively, in colorectal cancer." (PMID 34298879, 2021). "For colorectal cancer, analysis using the Oncomine database revealed significant difference only in NFIA and NFIB mRNA levels between tumor and normal samples." (PMID 32219034, 2020). "Expression of NFIA, NFIB and NIFC was reduced in colorectal cancer tissues evaluated based on mRNA HiSeq expression data from the TCGA database." (PMID 32219034, 2020). "Expression of NFIA and NFIB was downregulated in colorectal cancer according to the TCGA database." (PMID 32219034, 2020).
Hydrocephalus (4 papers, 2007 to 2020). Hydrocephalus is an active distension of the ventricular system of the brain resulting from inadequate passage of CSF from its point of production within the cerebral ventricles to its point of absorption into the systemic circulation. "The inability to identify intragenic mutations in NFIA in cases involving ACC, hydrocephalus, tethered cord syndrome, and urinary tract defects could suggest that the phenotype of heterozygous intragenic loss-of-function NFIA mutations might differ from that described here." (PMID 17530927, 2007). "NFIA is highly expressed in multiple regions of the human brain, including the embryonic and adult corpus callosum, and ACC and hydrocephalus were observed in Nfia−/− mutant mice." (PMID 17530927, 2007).
Macrocephaly (4 papers, 2016 to 2025). Occipitofrontal (head) circumference greater than 97th centile compared to appropriate, age matched, sex-matched normal standards. "Importantly, a balanced translocation patient DGAP104, in whom NFIA is disrupted at 1p31.3 also had macrocephaly." (PMID 26997977, 2016).
acute erythroid leukemia (3 papers, 2013 to 2023). An acute myeloid leukemia characterized by a predominant immature erythroid population. "The role of NFI members in AML have been very limited where only the NFIA fusion protein NFIA/CBFA2T3 has been reported in acute erythroid leukemia." (PMID 36572750, 2023).
bladder cancer (3 papers, 2017 to 2024). "In conclusion, our analysis confirmed that the ceRNA network YARS1‐hsa‐miR‐148b‐3p/hsa‐miR‐191‐5p‐NFIA/EFEMP1/TRAK2/PAFAH1B1 is associated with bladder cancer prognosis." (PMID 38506098, 2024). "In bladder cancer, elevated NFIA mRNA expression was associated with T1 progressive bladder cancer compared with T1 nonprogressive tumors." (PMID 32219034, 2020). "High expression of NFIA, NFIC and NFIX predicted worse survival outcome in patients with bladder cancer." (PMID 32219034, 2020). "Reduced mRNA expression of NFIA, NFIB and NFIX predicted better OS in bladder cancer." (PMID 32219034, 2020).
brain malformations (3 papers, 2020 to 2024). "Haploinsufficiency of NFIA has been associated with brain malformations and CAKUT, and upregulation could be a compensatory mechanism in Foxd2 KO cells." (PMID 38154558, 2024).
craniosynostosis (3 papers, 2023 to 2025). Craniosynostosis is defined as the premature fusion of one or more cranial sutures leading to secondary distortion of skull shape resulting in skull deformities with a variable presentation. "Here, the authors present a case of an infant boy with metopic craniosynostosis, polysyndactyly and speech delay resulting from a de novo, pathogenic, heterozygous variant in the NFIA gene." (PMID 40606574, 2025). "The authors report a case of a novel heterozygous pathogenic NFIA variant, in a young boy presenting with metopic craniosynostosis with preaxial polysyndactyly." (PMID 40606574, 2025). "This new NFIA variant is important for expanding the knowledge base of this rare condition, and the case strengthens the hypothesis that NFIA haploinsufficiency is a cause of craniosynostosis." (PMID 40606574, 2025). "Craniosynostosis has only on two occasions been described as a feature of 1p32-p31 deletion syndrome (with the NFIA gene encompassed by the multigenic deletion)." (PMID 40606574, 2025). "This is supported by the decision of the NHS Genomic Medicine Service in England to ‘green-list’ the connection between syndromic craniosynostosis and the NFIA gene." (PMID 40606574, 2025). "Craniofacial anomalies, such as asymmetries and craniosynostosis, are commonly observed in patients with NFIA haploinsufficiency." (PMID 37915986, 2023). "Genetic testing for NFIA may be warranted in craniosynostosis presentations where the routine genetic tests are negative." (PMID 40606574, 2025).
depression (3 papers, 2021 to 2024). "Gain-of-function experiments further demonstrated the regulatory mechanism of the miR-212/NFIA axis in depression." (PMID 34889698, 2021). "Nuclear factor I-A (NFIA) has been identified as the direct target for miR-212 which in turn regulates the level of the inflammatory factors TNF-α, IL-1β, and IL-6, which are generally associated with depression in human studies." (PMID 40655973, 2023). "miR-212 might play a protective role in depression by regulating apoptosis and inflammatory responses in mouse hippocampal neurons by targeting NFIA." (PMID 34889698, 2021). "Accordingly, miR-212 could ameliorate CUMS-induced depression-like behavior in mice by targeting NFIA, indicating its protective role in depression." (PMID 34889698, 2021). "We hypothesized that miR-212 might play a role in depression via regulating NFIA." (PMID 34889698, 2021). "Finally, functional experiments revealed that the protective effects of miR-212 in the CUMS depression model could be partially counteracted by NFIA overexpression, thus confirming the regulatory role of the miR-212/NFIA axis in depression development." (PMID 34889698, 2021). "First, we did not analyze the expression of miR-212/NFIA in patients with depression, and the correlation between miR-212/NFIA expression and clinicopathological parameters in patients with depression." (PMID 34889698, 2021). "In addition, we did not study the effect of NFIA alone on mice with depression." (PMID 34889698, 2021).
epilepsy (3 papers, 2023 to 2025). A brain disorder characterized by episodes of abnormally increased neuronal discharge resulting in transient episodes of sensory or motor neurological dysfunction, or psychic dysfunction. "Furthermore, overexpression of NFIA in astrocytes augmented the expression of inflammatory cytokines via the functional activity of TRPV4, thus aggravating neuroinflammation and exacerbating epilepsy." (PMID 37880726, 2023).
esophageal squamous cell carcinoma (3 papers, 2018 to 2022). Esophageal squamous cell carcinoma (ESCC) is a type of esophageal carcinoma (EC) that can affect any part of the esophagus, but is usually located in the upper or middle third. "NFIA was reduced in esophageal squamous cell carcinoma (ESCC), esophageal adenocarcinoma, and Barrett’s esophagus in Su2 and Kim’s datasets." (PMID 32219034, 2020). "The roles of NFIA and NFIB in esophageal squamous cell carcinoma (ESCC) and esophagogastric junction adenocarcinoma (EJA) remain poorly known." (PMID 29577671, 2018).
Sepsis (3 papers, 2017 to 2021). Sepsis is defined as life-threatening organ dysfunction caused by a dysregulated host response to infection. "NFIA has been acknowledged as a master molecular transcriptome regulator that modulates myeloid differentiation and maturation and acts as an immune defense mechanism during sepsis." (PMID 33932136, 2021).
acute monocytic leukemia (2 papers, 2020 to 2022). Acute monoblastic leukemia (AML-M5), is one of the most common subtypes of acute myeloid leukemia (AML) that is either comprised of more than 80% of monoblasts (AML-M5a) or 30-80% monoblasts with (pro)monocytic differentiation (AML-M5b). "The RP5-833A20.1/HSA-Mir-382-5p/NFIA pathway is critical for regulating cholesterol homeostasis and the inflammatory response in human acute monocytic leukemia macrophages." (PMID 36496794, 2022). "RP5-833A20.1 regulated the cholesterol homeostasis and inhibited inflammatory cytokines (TNF-α, IL-1β, and IL-6) in human acute monocytic leukemia macrophages by reducing expression of nuclear factor I A (NFIA), whose genomic location overlaps with RP5-883A20.1, by upregulating miR-382-5p." (PMID 32082313, 2020).
Alzheimer disease (2 papers, 2017 to 2023). A progressive, neurodegenerative disease characterized by loss of function and death of nerve cells in several areas of the brain leading to loss of cognitive function such as memory and language. "Using co-immunofluorescence staining of Alzheimer’s disease brain tissues, we confirmed pathologic downregulation of ERBB4 and transcription factor NFIA in reactive astrocytes." (PMID 37533101, 2023). "However, in Alzheimer’s disease brains, many SOX9+ astrocytes stained negative for NFIA." (PMID 37533101, 2023).
esophagogastric junction adenocarcinoma (2 papers, 2018 to 2020). "In a previous study, high NFIA expression was shown an independent predictor of poor prognosis in esophageal squamous carcinoma, and high NFIB expression was a negative prognostic value in esophagogastric junction adenocarcinoma." (PMID 32219034, 2020).
kidney cancer (2 papers, 2020 to 2022). Primary or metastatic malignant neoplasm involving the kidney. "For kidney cancer, Higgins’s dataset showed the NFIA mRNA expression level was upregulated in clear cell sarcoma of the kidney compared with normal kidney tissues." (PMID 32219034, 2020). "It is noteworthy that there was no absolute difference in the protein expression level of NFIA and SPRY1 between normal kidney tissues and kidney cancer." (PMID 36035369, 2022).
malignant glioma (2 papers, 2021 to 2025). A grade III or grade IV glioma arising from the central nervous system. "In a mouse model of malignant glioma, codeletion of SOX9 and POU3F2 regulatory enhancer elements in the nuclear factor IA (NFIA) locus block NFIA expression and inhibit tumorigenesis." (PMID 34012965, 2021).
melanoma (2 papers, 2017 to 2018). A malignant, usually aggressive tumor composed of atypical, neoplastic melanocytes. "A2058 human melanoma cells engineered to over-express either BRN2 or MITF were analyzed by qRT-PCR for expression of all four members of the NFI gene family, NFIA, NFIB, NFIC and NFIX." (PMID 28119061, 2017).
multiple sclerosis (2 papers, 2022 to 2025). A progressive autoimmune disorder affecting the central nervous system resulting in demyelination. "In addition, it has been reported that the NFIA protein is highly expressed in reactive astrocytes during human neurological injury, such as multiple sclerosis, hypoxic-ischemic encephalopathy, and spinal cord, but the expression of NFIA in TON has not been reported." (PMID 36254157, 2022).
neuroblastoma (2 papers, 2009 to 2025). Neuroblastoma (NB) is the most common solid, extracranial childhood tumor. "We found that the CDON regulatory region was occupied by NFIA and NFIB, aligning with findings that NFIB represses CDON in neuroblastoma cells." (PMID 39617063, 2025).
Obesity (2 papers, 2020 to 2023). Accumulation of substantial excess body fat. "Altogether, these results provide a mechanistic insight into multiple layers of gene regulation by NFIA during brown adipocyte differentiation and an implication for the development of anti-obesity therapy." (PMID 32991581, 2020).
schizophrenia (2 papers, 2013 to 2025). A major psychotic disorder characterized by abnormalities in the perception or expression of reality. "Astrocytes differentiate via nuclear factor I-A, Sox9, and Notch pathways, occurring within a neuronal environment that may already be compromised in the early stages due to the genetic factors associated with the ‘two-hits’ model of schizophrenia." (PMID 40427508, 2025).
tongue squamous cell carcinoma (2 papers, 2020 to 2021). A squamous cell carcinoma that arises from the tongue. "Of the downregulated genes in OSCC-GB, a significant decrease in the expression of NFIA was noted in tongue squamous cell carcinoma that was associated with poor overall survival in head and neck cancer." (PMID 33980865, 2021). "Ye’s dataset showed significantly decreased NFIA and NFIB mRNA expression level in tongue squamous cell carcinoma." (PMID 32219034, 2020).
and developmental disabilities (1 paper, 2022). "NFIA haploinsufficiency can be suspected by a careful observation of the dysmorphisms (macrocephaly, craniofacial, and first-finger anomalies), and this potential diagnosis is strengthened by the presence of intellectual and developmental disabilities or other neurodevelopmental disorders." (PMID 36553517, 2022).
Anxiety (1 paper, 2020). Intense feelings of nervousness, tension, or panic often arise in response to interpersonal stresses. "TCF4 is a phenotype seed gene for DD, ID, ASD, speech delay, GI problems, dental, Pes planus, hypotonia, and facial dysmorphisms; NFIA is a phenotype seed gene for anxiety, GI problems, and hypotonia; and RGMB appears as a phenotype seed gene for ASD." (PMID 33282601, 2020).
asthma (1 paper, 2021). "A genetic variant of nuclear factor I/A(NFIA) gene in the 1p31 chromosomal region is significantly associated with combined asthma and AR phenotype." (PMID 34946955, 2021).
cecum adenocarcinoma (1 paper, 2020). "However, NFIA expression was increased in rectal mucinous adenocarcinoma and cecum adenocarcinoma in Kaiser’s study." (PMID 32219034, 2020).
Cerebral ischemia (1 paper, 2022). Restriction of arterial blood supply to the brain associated with insufficient oxygenation to support the metabolic requirements of the tissue. "In addition, miRNA can play a role through targeted regulation of NFIA, for example, miR-424 can prevent astrocyte proliferation after cerebral ischemia/reperfusion in elderly mice by regulating NFIA." (PMID 36254157, 2022).
cholestasis (1 paper, 2025). Impairment of the bile flow caused by obstruction within the liver, or outside the liver in the bile duct system. "Furthermore, in group comparisons expression of NFIA but not of the other NFI genes was lower with alcohol use, elevated levels of CRP (inflammation), cholestasis and the use of CYP inducers." (PMID 41106572, 2025).
chromosome deletion syndrome (1 paper, 2017). "This condition has recently been annotated as “1p32p31 chromosome deletion syndrome” (OMIM 613735), and it has been suggested that the phenotype is the result of haploinsufficiency of the NFIA gene." (PMID 28926972, 2017).
clear cell carcinoma (1 paper, 2020). "For example, the expression of NFIA and NFIB was reduced in kidney chromophobe cell carcinoma but not in papillary or clear cell carcinoma; however, mRNA expression levels were elevated." (PMID 32219034, 2020).
esophageal carcinoma (1 paper, 2017). A primary or metastatic malignant neoplasm involving the esophagus. "miR-29a significantly reduced esophageal carcinoma cell proliferation and migration by inhibiting NFIA." (PMID 28323865, 2017).
head and neck cancer (1 paper, 2020). A primary or metastatic malignant neoplasm affecting the head and neck. "Decreased expression levels of NFIA, NFIB and NFIC were associated with poor overall survival (OS) in head and neck cancer." (PMID 32219034, 2020). "Head and neck cancer patients with NFIA gene alteration showed better OS compared with head and neck cancer patients without NFIA gene alteration." (PMID 32219034, 2020).
infiltrating bladder urothelial carcinoma (1 paper, 2020). An invasive transitional cell carcinoma that arises from the urinary bladder urothelium. "NFIA, NFIB and NFIC expressions were decreased in both superficial bladder cancer and infiltrating bladder urothelial carcinoma compared with normal tissues in Lee, Sanchez-Carbayo2 and Blaveri2’s studies." (PMID 32219034, 2020).